KIF15 (kinesin family member 15)
Diseases named in the same sentence as KIF15 in open-access papers (continued):
Sharing a sentence is not in itself a finding about the gene and the disease.
prostate carcinoma (continued). "Moreover, we found that down-regulation of KIF15 expression significantly inhibited the proliferation of prostate cancer cells, as well as promoted prostate cancer cell apoptosis." (PMID 37658042, 2023). "Further, according to the results of colony formation and Transwell assay, we found that down-regulation of KIF15 expression could significantly inhibit the colony formation ability and mobility of prostate cancer cells." (PMID 37658042, 2023). "Therefore, we chose KIF15 as the research object to explore its possible influence on the progression of prostate cancer." (PMID 37658042, 2023). "The inhibition of prostate cancer development by KIF15 knockdown was also assured in vivo." (PMID 37658042, 2023). "Furthermore, data collected from the TCGA-PRAD dataset also indicated the upregulation of KIF15 in prostate cancer tissues compared with normal ones, as well as its negative correlation with patients’ overall survival and progression-free survival." (PMID 37658042, 2023). "Moreover, the involvement of the PI3K/Akt pathway in the KIF15-mediated regulation of prostate cancer was preliminarily proved." (PMID 37658042, 2023). "KIF15 may play an important role in the development of prostate cancer." (PMID 37658042, 2023). "Furthermore, KIF15 was reported to directly bind to the N-terminus of androgen receptor (AR)/AR-V7 and prevent the degradation of AR/AR-V7 proteins, which contributed to enzalutamide resistance in prostate cancer." (PMID 36807568, 2023). "Kinesin family member 15 (KIF15) facilitates the interaction between USP14 and AR/AR-V7, promoting enzalutamide resistance in prostate cancer cells." (PMID 38702734, 2024). "Before constructing cell models, the endogenous expression of KIF15 in immortalized cells of human normal prostate matrix WPMY-1 and human prostate cancer cell lines, including PC-3, DU 145, and C4-2, was detected by qPCR and western blot analysis, respectively." (PMID 37658042, 2023). "Correspondingly, it was demonstrated that the inhibited cell proliferation and strengthened cell apoptosis induced by KIF15 knockdown could be partially rescued by SC79 treatment, indicative of the involvement of PI3K/Akt pathway in KIF15-mediated prostate cancer development." (PMID 37658042, 2023). "However, the role of KIF15 in prostate cancer has not been reported." (PMID 37658042, 2023). "Furthermore, relative to the non-castration-resistant prostate cancer cell line (LNCaP), the expression of KIF14, CENPE, KIF15, KIF18B, and KIFC1 was significantly elevated in the castration-resistant PCa cell line (DU145)." (PMID 40956849, 2025).
idiopathic pulmonary fibrosis (5 papers, 2021 to 2023). Idiopathic pulmonary fibrosis (IPF) is a nonneoplastic pulmonary disease that is characterized by the formation of scar tissue within the lungs in the absence of any known cause. "A new clinical study reported that a Kif15 mutation contributes to idiopathic pulmonary fibrosis, which is closely associated with the function of Kif15 in regulating cell proliferation." (PMID 37799807, 2023). "KIF15 variants are also linked to Idiopathic Pulmonary Fibrosis susceptibility." (PMID 37266661, 2023). "Common and rare genetic variants at the KIF15 (kinesin family member 15) gene, and a rare variant in SPDL1 (spindle apparatus coiled-coil protein 1) have also been associated with pulmonary fibrosis." (PMID 37965228, 2023). "This might also obscure the finding that none of the patients with the KIF15 missense variant had a known family history of pulmonary fibrosis despite the early onset of the disease." (PMID 37777755, 2023).
lung adenocarcinoma (5 papers, 2013 to 2021). A carcinoma that arises from the lung and is characterized by the presence of malignant glandular epithelial cells. "Increased KIF15 expression indicates poor prognosis and disordered cell cycle of lung adenocarcinoma." (PMID 33985517, 2021). "Elevated KIF15 expression can predict a poor prognosis in patients with lung adenocarcinoma." (PMID 32322172, 2020).
epithelial ovarian cancer (4 papers, 2019 to 2023). "Likewise, in the Oncomine database, the expression level of KIF15 was significantly increased in bladder, brain and CNS, breast, cervical, colorectal, esophageal, gastric, head and neck, lung, and ovarian cancers, as well as lymphoma and sarcoma; while significantly decreased in leukemia." (PMID 35359374, 2022). "Univariate and multivariate analyses of the correlation of CDCA5, FOXM1, KIF15, MCM2, and ZWINT expression with overall survival (OS) among epithelial ovarian cancer patients." (PMID 31708970, 2019). "Notably, in separate but parallel investigations conducted by our team, we observed significant vulnerability of the spindle assembly motor proteins KIF11 and KIF15 and their binding partner TPX2 in epithelial ovarian cancer (unpublished data)." (PMID 37894278, 2023).
gastric cancer (4 papers, 2020 to 2024). A primary or metastatic malignant neoplasm involving the stomach. "A study constructed a decision tree using mutations in PIK3CA, MEF2C, SLC11A1, and KIF15 to divided patient sub-cohorts with elevated PD-L1 expression, which contribute to identify the novel prognostic biomarkers of Gastric Cancer." (PMID 35359374, 2022). "However, the function of KIF15 in gastric cancer (GC) is still unclear." (PMID 32322172, 2020).
glioma (4 papers, 2015 to 2025). A benign or malignant brain and spinal cord tumor that arises from glial cells (astrocytes, oligodendrocytes, ependymal cells). "As previously reported, the knockdown of Kif15 inhibits cell proliferation, promotes cell apoptosis, and causes cell cycle arrest in glioma cells." (PMID 35370541, 2022).
lung carcinoma (4 papers, 2015 to 2025). "Taken together, these studies suggest KIF15 has therapeutic potential in lung cancer, particularly LUAD, due to its positive regulation of oncogenic signalling pathways." (PMID 40002279, 2025). "Multiple studies have indicated KIF15’s functional relevance in lung cancer." (PMID 40002279, 2025). "Furthermore, abnormal high expression of KIF15 could predict a poor prognosis in patients with lung carcinoma." (PMID 32322172, 2020). "In addition, similar to lung cancer, the follow-up data of all 122 GC tissues in our biobank showed that patients with high expression level of KIF15 had lower 5-year survival rate than patients with low expression level of KIF15." (PMID 32322172, 2020). "Given its functions in mitosis, KIF15 inhibition is likely to influence genomic stability; however, the effects of its inhibition on CIN and mitotic phenotypes remain to be determined in lung cancer cells." (PMID 40002279, 2025). "Also specific to the epithelial compartment, we observed enrichment for a signature conferring poor outcome in lung cancer, which included general cancer prognostic genes like AURKB, EXO1, MAD2L1, CDCA8, and kinesins like KIF15." (PMID 32883324, 2020).
bladder cancer (3 papers, 2020). "Herein, as a potential downstream target of GSG2, KIF15 was found to possess similar effects with GSG2 on bladder cancer development." (PMID 32439830, 2020). "In conclusion, our study showed, as the first time, GSG2 as a prognostic indicator and tumor promotor for bladder cancer, whose function was carried out probably through the regulation of KIF15." (PMID 32439830, 2020). "For example, KIF15 is reported that it can accelerate cell growth of bladder cancer through MEK-ERK signaling pathway." (PMID 32549756, 2020). "Consistently, the endogenous expression of KIF15 in bladder cancer cell lines was found to be significantly higher than that in HCV29 cell line as detected by qPCR." (PMID 32439830, 2020). "In conclusion, we found the upregulated expression of GSG2 and KIF15 in tumor tissues and cancer cell lines of bladder cancer." (PMID 32439830, 2020). "More importantly, experimental evidence proved that GSG2 may regulate bladder cancer through its downstream target KIF15." (PMID 32439830, 2020). "The potential role of KIF15 in bladder cancer was next investigated by data mining of TCGA database and IHC analysis of clinical specimens, both of which suggested its upregulation in bladder cancer." (PMID 32439830, 2020). "Additionally, the investigation of regulatory mechanism of GSG2 on bladder cancer identified KIF15 as a potential downstream of GSG2." (PMID 32439830, 2020). "Knockdown of KIF15 could significantly inhibit cell proliferation and cell migration of bladder cancer, while promoting cell apoptosis." (PMID 32439830, 2020). "Additionally, MEK inhibition has been proposed as a promising strategy in bladder cancers with high expression of KIF15, which upregulates the MEK pathway." (PMID 33216841, 2020). "More importantly, KIF15 knockdown could alleviated the promotion of bladder cancer by GSG2 overexpression." (PMID 32439830, 2020). "Both GSG2 and KIF15 could act as tumor promotor in the development and progression of bladder cancer, through promoting cell proliferation, colony formation, cell migration and suppressing cell apoptosis." (PMID 32439830, 2020). "Therefore, it was functionally illustrated that KIF15 may be a target of GSG2 in the regulation of bladder cancer." (PMID 32439830, 2020). "Furthermore, our study revealed that knockdown of KIF15 could inhibit development of bladder cancer in vitro, and alleviate the GSG2 overexpression induced promotion of bladder cancer." (PMID 32439830, 2020).
leiomyosarcoma (3 papers, 2022 to 2025). An uncommon, aggressive malignant smooth muscle neoplasm, usually occurring in post-menopausal women. "USP15 interacts with DEK and the kinesin family member 15 (KIF15) and stabilizes DEK to facilitate the proliferation of the leiomyosarcoma cell lines SK-UT-1 and SK-LMS-1." (PMID 35203682, 2022). "Additionally, KIF15 recruits and promoted the binding between USP15 and DEK, facilitating the proliferation of leiomyosarcoma cells by preventing DEK degradation." (PMID 40087774, 2025).
melanoma (3 papers, 2019 to 2021). A malignant, usually aggressive tumor composed of atypical, neoplastic melanocytes. "High expression of KIF15 in melanoma was also observed by Yu’s group, whose report illuminated the positive role of KIF15 in the tumorigenicity of melanoma." (PMID 32439830, 2020). "In melanoma, KIF15 was found to be significantly upregulated in cancer cells and tissues and the suppression of KIF15 remarkably reduced tumor growth and increased the apoptosis of cancer cells." (PMID 31729978, 2019). "KIF15 also plays a role in promoting the tumorigenicity of melanoma." (PMID 33985517, 2021).
osteosarcoma (3 papers, 2018 to 2023). A usually aggressive malignant bone-forming mesenchymal neoplasm, predominantly affecting adolescents and young adults. "In contrast to U-2OS and HOS, the remaining four osteosarcoma cell lines did not develop STLC resistance despite their expression of KIF15." (PMID 30557316, 2018). "We were able to obtain STLC-resistant cells from two osteosarcoma cell lines out of six examined, and show that their resistance was in fact mostly dependent on KIF15, whereas stable resistance was not acquired by the remaining four cell lines, despite KIF15 expression." (PMID 30557316, 2018).
colorectal cancer (2 papers, 2020 to 2024). A primary or metastatic malignant neoplasm that affects the colon or rectum. "Further research revealed that B7-H3/KIF15, through activation of the ERK1/2 signaling pathway, promoted radiation resistance in colorectal cancer." (PMID 38952550, 2024).
endometrial cancer (2 papers, 2022 to 2025). Primary or metastatic malignant neoplasm involving the endometrium (mucous membrane that lines the endometrial cavity). "Abnormal DNA replication is a hallmark of the cancer process, and previous studies have indicated that KIF15 and other kinesin genes were significantly enriched in DNA replication in bladder and endometrial cancers." (PMID 35359374, 2022). "However, KIF15 knockdown inhibites the development of endometrial cancer by restraining the Wnt/β-catenin signaling." (PMID 40087774, 2025).
fibrosis (2 papers, 2023 to 2024). the formation of excess fibrous connective tissue in an organ or tissue in a reparative or reactive process. "For the first time, we have elucidated that FoxO6 in CMs promotes pathological cardiac fibrosis induced by pressure overload largely by activating Kif15, which contributes to TGF‐β1 secretion." (PMID 37799807, 2023).
liver cancer (2 papers, 2022 to 2025). An epithelial or non-epithelial malignant neoplasm that arises from the liver. "Studies have found that PSMD12 promotes the development of liver cancer by upregulating KIF15 and promoting the activation of the MEK-ERK pathway." (PMID 41444773, 2025). "To further investigate the role of KIF15 in liver cancer, we used KIF15 siRNA to decrease the expression of KIF15 protein in HepG2 and Huh7 cells and detected the biological functions of these cells." (PMID 36137220, 2022). "The result was consistent with TCGA data analysis, and KIF15 expression was highly increased in liver cancer tissues with high levels of PSMD12." (PMID 36137220, 2022). "The results showed that the mRNA expression of KIF15 in liver cancer tissues was significantly higher than that in normal liver tissues." (PMID 36137220, 2022). "To explore the functions of KIF15 in liver cancer, we assessed the expression of KIF15 mRNA in liver cancer and normal tissues from TCGA." (PMID 36137220, 2022). "Interestingly, we found that KIF15 also activates the MEK-ERK signaling pathway in liver cancer and can promote the malignant progression of HCC cells." (PMID 36137220, 2022). "To test our hypothesis, we conducted a rescue experiment and observed that knockdown of KIF15 in PSMD12-overexpressing liver cancer cells can restore the progression of tumor malignancy and the activation of the MEK-ERK signaling pathway induced by PSMD12." (PMID 36137220, 2022). "In addition, we found that PSMD12 can promote the activation of the MEK-ERK pathway in liver cancer cells by upregulating the expression of KIF15, which is a member of the kinesin family, thereby promoting the malignant progression of tumors." (PMID 36137220, 2022). "In addition, knockdown of PSMD12 in liver cancer cells results in a decrease in KIF15 expression, while overexpression of PSMD12 increases the protein level of KIF15." (PMID 36137220, 2022). "Moreover, based on the mRNA data and clinical information from TCGA-LIHC, we found that the expression of KIF15 mRNA was negatively related to the OS of liver cancer patients, and the prognosis of patients with high KIF15 was significantly worse than that of patients with low KIF15." (PMID 36137220, 2022). "Subsequently, we performed IHC to detect the expression of KIF15 and PSMD12 in liver cancer tissues." (PMID 36137220, 2022). "In summary, our study shows that in liver cancer cells, PSMD12 promotes the expression of KIF15, thereby regulating the activation of MEK-ERK to promote malignant tumor progression." (PMID 36137220, 2022). "Interestingly, the western blot analysis results showed that knockdown of KIF15 highly inhibited the expression of p-MEK and p-ERK in HepG2 and Huh7 cells, indicating the functions of KIF15 in activating the MEK-ERK pathway in liver cancer cells." (PMID 36137220, 2022).
sarcoma (2 papers, 2022 to 2023). A usually aggressive malignant neoplasm of the soft tissue or bone. "Interestingly, our analyses found that both KIF11 and KIF15 were highly expressed across all the various sarcomas included in the portal." (PMID 37894278, 2023).
Anxiety (1 paper, 2025). Intense feelings of nervousness, tension, or panic often arise in response to interpersonal stresses. "These mice exhibited anxiety-like behavior, which persisted until 9 months, indicating that the emotional changes caused by Kif15 deletion in mice become more complex and varied with age." (PMID 40892874, 2025).
bipolar disorder (1 paper, 2025). A disorder of the brain that causes unusual shifts in mood, energy, activity levels and the ability to carry out day-to-day tasks. "In conclusion, our study has identified a microtubule-associated molecular motor, KIF15, that plays a novel role in bipolar disorder through its contributions to spine morphology and function." (PMID 40892874, 2025). "In summary, our study revealed a novel role of Kif15 on the emotion, and also provided a new clinical target for the pathogenesis of bipolar disorder." (PMID 40892874, 2025). "After adulthood, the expressions of excitatory and inhibitory synaptic proteins in Kif15-/- mice increased, which may be one of the reasons why Kif15-/- mice develop bipolar disorders like behavior." (PMID 40892874, 2025). "Previous studies have reported that GABRB1 is associated with bipolar disorder, and our data also revealed the notable increases of the inhibitory postsynaptic scaffolding protein Gephyrin and inhibitory receptor of GABRB1 in the Kif15-/- mice." (PMID 40892874, 2025).
cardiac hypertrophy (1 paper, 2023). "FoxO6 cKO significantly inhibited cardiac hypertrophy and fibrotic remodeling and improved cardiac function, which was achieved by inhibiting the expression of Kif15." (PMID 37799807, 2023).
COVID-19 (1 paper, 2023). A disease caused by infection with severe acute respiratory syndrome coronavirus 2. "In our study, the levels of CDC6, CDC25C, and KIF15 were down-regulated in both the COVID-19 and SLE datasets, suggesting a better prognosis with these genes." (PMID 37426642, 2023). "The area under the curve (AUC) values for 6 shared hub genes (CDC6, PLCG1, KIF15, LCK, CDC25C, and RASGRP1) in the SLE dataset to discriminate between patients and healthy controls were greater than 0.61, while those for the COVID-19 dataset were greater than 0.91." (PMID 37426642, 2023).
depression (1 paper, 2025). "A GWAS study in a European population showed that there were variants in both exons and introns of the KIF15 gene on chromosome 3 in patients with depression." (PMID 40892874, 2025). "Additionally, a SNP variant in the intron of KIF15 gene was also found in another GWAS of depression patients from multi-ancestry." (PMID 40892874, 2025). "Our previous study reported that Kif15 knockout mice did be prone to depression, and the basic morphology and molecular mechanism need to further clarify." (PMID 40892874, 2025). "Previous GWAS analysis showed KIF15 gene is a candidate gene for depression, but the molecular mechanism is unknown." (PMID 40892874, 2025).
developmental delay (1 paper, 2025). "In the hippocampus, although the total dendritic spines were similar to that of the wild type, the density of mushroom dendritic spines in Kif15-/- mice of 11 weeks old was still less than that in WT mice, suggesting that the Kif15-/- mice still had developmental delay in adulthood." (PMID 40892874, 2025).
Ewing sarcoma (1 paper, 2023). A small round cell tumor that lacks morphologic, immunohistochemical, and electron microscopic evidence of neuroectodermal differentiation. "Furthermore, bioinformatic analysis of RNA expression data from solid cancers within DepMap portal indicated that KIF15 expression levels were the highest in Ewing sarcoma and that KIF11 expression levels were the second highest in Ewing sarcoma, only behind synovial sarcomas." (PMID 37894278, 2023).